DNHD1 (dynein heavy chain domain 1)
Description:
Essential for the normal assembly and function of sperm flagella axonemes.
Synonyms: C11orf47; CCDC35; DHCD1; DNHD1L; FLJ32752; FLJ46184; FLJ35709; DKFZp686J0796; SPGF65
Tractability: No criterion of Open Targets' tractability assessment is met for any kind of drug.
Gene: Protein-coding gene on chromosome 11 (6,497,260 to 6,593,758, forward strand). Ensembl gene ENSG00000179532.
Subcellular location: Cell projection, cilium, flagellum
Subcellular location (Human Protein Atlas): Mid piece; Annulus
Gene Ontology:
Molecular function: dynein intermediate chain binding; dynein light intermediate chain binding; minus-end-directed microtubule motor activity; ATP binding
Biological process: flagellated sperm motility; sperm flagellum assembly; microtubule-based movement
Cellular component: extracellular exosome; sperm annulus; sperm flagellum; sperm midpiece; inner dynein arm; dynein complex; motile cilium
Genetic constraint (gnomAD): Loss-of-function variants: 384 observed, 465.98 expected, observed/expected ratio (o/e) 0.82, 90% interval 0.76 to 0.9. The upper end of that interval is the gene's LOEUF score, 0.9, which puts it in group 3 of 6, group 1 being the genes least tolerant of losing a copy. Missense variants: 5,334 observed, 6,040.5 expected, observed/expected ratio (o/e) 0.88, 90% interval 0.86 to 0.9. Synonymous variants: 2,202 observed, 2,458.5 expected, observed/expected ratio (o/e) 0.9, 90% interval 0.86 to 0.93.
Homologues: Orthologues: chimpanzee DNHD1 (99% identical), macaque DNHD1 (96% identical), rabbit DNHD1 (77% identical), guinea pig DNHD1 (72% identical), mouse Dnhd1 (68% identical), rat Dnhd1 (68% identical), zebrafish dnhd1 (23% identical). Paralogues in human: DNAH9 (16% identical), DNAH11 (16% identical), DNAH10 (16% identical), DNAH1 (16% identical), DNAH5 (16% identical), DNAH17 (16% identical), DNAH2 (16% identical), DNAH6 (16% identical), DNAH12 (15% identical), DNAH8 (15% identical), DNAH14 (15% identical), DNAH3 (15% identical), and 3 more.
Diseases named in the same sentence as DNHD1 in open-access papers:
DNHD1 is named in the same sentence as 14 diseases in open-access papers, as found by Europe PMC text mining. Sharing a sentence is not in itself a finding about the gene and the disease. The quoted sentences say what the papers report.
Hodgkins lymphoma (1 paper, 2025). A heterogeneous group of malignant lymphoid neoplasms of B-cell origin characterized histologically by the presence of Hodgkin and Reed-Sternberg (HRS) cells in the vast majority of cases. "In case #4 (B-ALL), along with his father and paternal uncle who had Hodgkin’s lymphoma, we detected variants of both ETAA1 and DNHD1 genes." (PMID 40995433, 2025).
Infertility (1 paper, 2023). "This support the hypothesis that the identified missense DNHD1 variants may be responsible for the observed infertility phenotypes." (PMID 36768883, 2023).
synovial sarcoma (1 paper, 2025). "Thyroid papillary carcinoma and synovial sarcoma developed in the father, both of which could be related to the germline DNHD1 variant." (PMID 40995433, 2025).
DNHD1 also shares sentences with these, for which no sentence is quoted: colorectal cancer (1 paper); depression (1); hematologic malignancies (1); Intellectual disability (1); lymphoma (1); male infertility (1); pancreatic adenocarcinoma (1); pancreatic cancer (1); soft tissue sarcoma (1); Thyroid papillary carcinoma (1); tumor (1).